UCA1 (urothelial cancer associated 1)
Diseases named in the same sentence as UCA1 in open-access papers (continued):
Sharing a sentence is not in itself a finding about the gene and the disease.
hepatocellular carcinoma (58 papers, 2015 to 2025). A malignant tumor that arises from hepatocytes. "Genes such as urothelial cancer associated 1 (UCA1) which participated in bile secretion pathway were overexpressed in hepatocellular carcinoma (HCC) tissues." (PMID 33050883, 2020). "Simultaneously, UCA1 also remarkably associated with prognosis of patients with different cancer and may be a potential diagnosis biomarker in hepatocellular cancer, CRC and GC." (PMID 30918102, 2019). "Of note for hepatocarcinogenesis associated with HBV infection, UCA1 was found to be frequently upregulated in HBx-positive tissues and was shown to be upregulated by HBx in hepatoma cells, thus promoting cell growth by facilitating G1/S transition through CDK2." (PMID 29495592, 2018). "LncRNA MFI2-AS1 is in clinical trials for use as a diagnostic biomarker for kidney cancer, and lncRNAs UCA1 and WRAP53 are in clinical trials for use as diagnostic biomarkers for hepatocellular carcinoma." (PMID 37891744, 2023). "OSGIN1 was regulated by long non-coding RNA (lnRNA) UCA1 to mitigate autophagy flux-mediated apoptosis through the mTOR pathway in human hepatocellular carcinoma cells (HepG2) under arsenic toxicity." (PMID 35625730, 2022). "Previous studies showed that UPF1 inhibits the hepatocellular carcinoma progression by targeting MRP2/ABCC2 or long non-coding RNA UCA1." (PMID 34922601, 2021). "In hepatocellular carcinoma, miR-216b targets UCA1 and represses cancer progression by inactivating the ERK signaling pathway." (PMID 34733326, 2021). "The knockdown of UCA1 in hepatoma cells decreased the binding of EZH2 and H3K27me3 on the p27 promoter and significantly suppressed tumor growth in a xenograft mouse model." (PMID 34206504, 2021). "The ‘-231 ~ -222’ bp region in the promoter of UCA1 is the main binding site of MYB transcription factor in hepatocellular carcinoma cells (HCC)." (PMID 34876130, 2021). "Evaluated UCA1 contributes to progression of hepatocellular carcinoma through decreasing miR-216b and activation the FGFR1/ERK signaling pathway." (PMID 27893417, 2017). "Although we provided evidence to show that HBx upregulated UCA1 and UCA1 functioned as an oncogene in this study, we noted that UCA1 only elevated in a portion of hepatoma cell lines." (PMID 27009634, 2016). "Knock down of UCA1 in HBx-expressing hepatic and hepatoma cells resulted in markedly increased apoptotic cells by elevating the cleaved caspase-3 and caspase-8." (PMID 27009634, 2016). "In summary, we discovered that UCA1, upregulated by HBx, displayed a crucial role in G1/S transition in both hepatic and hepatoma cells." (PMID 27009634, 2016). "In hepatocellular carcinoma, upregulated UCA1 contributes to the progression of cancer by counteracting the inhibitory effect of miR-216b and activating the FGFR1/ERK signaling pathway." (PMID 28074092, 2016). "Urothelial Cancer Associated 1 (UCA1) can activate the expression of transcription factor Snail2 by acting as the ceRNA of miR-203, thus promoting the proliferation, invasion, and EMT of hepatoma cells." (PMID 34758879, 2021). "UCA1 could act as an endogenous sponge by directly binding to miR-216b and downregulating miR-216b expression in hepatocellular carcinoma cell." (PMID 28969024, 2017). "We also show that knockdown of UCA1 in hepatoma cells inhibits tumorigenesis in nude mice." (PMID 27009634, 2016). "We showed that UCA1 expressed in a group of hepatoma cells, i.e., Huh7, HepG2 and Hep3B cells." (PMID 27009634, 2016). "We then examined the mRNA levels of HBx and UCA1 in 9 other hepatoma cell lines by RT-PCR." (PMID 27009634, 2016). "We did not perform subgroup analyses for esophageal squamous cell carcinoma or hepatocellular carcinoma, because no more than one study each investigated these associations between UCA1 and OS." (PMID 27329842, 2016).
hepatocellular carcinoma (continued). "Previous studies have highlighted the importance of lncRNA UCA1 in various cancers, particularly gastrointestinal (GI) cancers and hepatocellular carcinoma (HCC)." (PMID 39937792, 2025). "Moreover, lncRNA UCA1 is physically linked to the enhancer of zeste homolog 2 (EZH2), which inhibits p27Kip1 through histone methylation (H3K27me3) in p27Kip1 promoter, thus promoting tumorigenesis in nude mice in hepatocellular carcinoma." (PMID 34868904, 2021). "We aimed to elucidate the diagnostic efficacy of eight serum lncRNAs HULC, MALAT1, Linc00152, PTENP1, PTTG3P, SPRY4-IT1, UBE2CP3, and UCA1 and their combinations for the diagnosis of hepatocellular carcinoma (HCC)." (PMID 32733618, 2020). "However, the biological role and clinical significance of UCA1 in the carcinogenesis of hepatocellular carcinoma (HCC) remain unclear." (PMID 25760077, 2015). "All lncRNAs selected in this study have established roles in HCC pathogenesis, UCA1, GAS5, LINC00152, and LINC00853, were chosen based on their established functional relevance in hepatocellular carcinoma (HCC) and their demonstrated potential as diagnostic biomarkers." (PMID 39609501, 2024). "For example, SEs-associated lncRNAs such as LINC01503 in squamous cell carcinoma (SCC), lncRNA HCCL5 in Hepatocellular carcinoma (HCC), lncRNA UCA1 in Epithelial Ovarian Cancer, have been revealed in cancer." (PMID 37385987, 2023). "Knockdown of UCA1 ameliorated the effect of UPF1 knockdown on HCC growth and invasion, indicating that UCA1 mediates the effect of UPF1 on the invasion and proliferation of hepatocellular carcinoma cells." (PMID 33732285, 2021). "In a study carried out on hepatocellular carcinoma tissues, a significant positive correlation was found between the expression levels of FGFR1 protein and those of UCA1." (PMID 31319040, 2020). "UCA1 increases cell proliferation through KLF4-KRT6/13 signaling pathway and FGFR1/ERK signaling pathway, respectively, in prostate cancer and hepatocellular carcinoma." (PMID 27713161, 2017). "Further studies show that the upregulated UCA1 promotes cell growth by facilitating G1/S transition through CDK2 in both hepatic and hepatoma cells." (PMID 27009634, 2016). "More importantly, we observed an inverse correlation between the p27 mRNA expression and UCA1 in HCC tissues, and silence of UCA1 in HBx-expressing hepatoma cells leading to suppression of tumour growth in nude mice." (PMID 27009634, 2016). "Previous evidence showed that lncRNA UCA1 was up-regulated in hepatocellular carcinoma, and EZH2 showed a negative correlation with lncRNA UCA1 level." (PMID 34868904, 2021). "Thus, by increasing UCA1, HBx can contribute to CDK2-mediated proliferation of hepatoma cells." (PMID 34206504, 2021). "On the other hand, some non-HBx-expressing hepatoma cells (e.g. Huh-7, HepG2) also expressed UCA1." (PMID 27009634, 2016). "Apart from these, lncRNA UCA1 has been detected to be overexpressed in various cancers, particularly GI cancers, such as CRC, esophageal squamous cell carcinoma (ESCC), hepatocellular carcinoma (HCC), and GC." (PMID 33936199, 2021).
lung cancer (58 papers, 2014 to 2025). A malignant neoplasm involving the lung. "Curcumin and usnic acid downregulate urothelial carcinoma-associated 1 (UCA1), which is upregulated in gastric and lung cancer and promotes proliferation by sponging miR-26a-5p and miR-144-3p, respectively." (PMID 37190145, 2023). "Some of these lncRNAs like FENDRR (FOXF1 adjacent non-coding developmental regulatory RNA), UCA1(urothelial cancer associated 1) have been reported to play roles in lung cancer development." (PMID 31374807, 2019). "The association between UCA1 and lung cancer has been confirmed by recent experimental observation that UCA1 provided the highly diagnostic performance for detection of non-small cell lung cancer." (PMID 27028993, 2016). "In a previous study, we compared the expression of lncRNAs in gefitinib-sensitive and gefitinib-resistant human lung cancer cells by lncRNA microarray analysis, and found that some lncRNAs, including UCA1 (urothelial cancer-associated 1), were up-regulated in resistant cells." (PMID 26160838, 2015). "Furthermore, overexpression of UCA1 was associated with shorter survival in lung cancer." (PMID 31777598, 2019). "In lung cancer, UCA1 promotes tumor growth, metastasis, and resistance to therapy by modulating cell proliferation, apoptosis, and DNA repair mechanisms." (PMID 39201688, 2024). "UCA1: UCA1 is an oncogenic lncRNA implicated in COPD pathogenesis and lung cancer progression, whose dysregulated expression contributes to disease aggressiveness and poor clinical outcomes." (PMID 39201688, 2024). "CUR (25–100 μM, for 6–48 h) also inhibited lung cancer cell growth by down‐regulating UCA1, and by enhancing miRNA‐98 activity." (PMID 37697969, 2023). "In lung adenocarcinoma and non‐small cell lung cancer, the overexpression of UCA1 indicates a poor prognosis for patients." (PMID 37321562, 2023). "Overexpression of lncRNA UCA1 significantly promoted lung cancer cell viability, migration, invasion, and cell cycle progression, but promoted cell apoptosis by upregulating PBX3 via sponging miR‐144." (PMID 35068042, 2022). "Differential expression patterns and levels of the LncRNA SOX2‐OT, in contrast to other LncRNAs (GLI1‐AS, GAS5, ZEB1‐AS and UCA1), were identified in several lung cancer cell lines at baseline cellular culture conditions." (PMID 33433063, 2021). "Our results demonstrated that miR‐138 and miR‐193 affect cell function by directly targeting and regulating UCA1 in lung cancer." (PMID 32767514, 2020). "Correlations between miR‐138 or miR‐193 and UCA1 in lung cancer tissues was assessed using quantitative real‐time PCR." (PMID 32767514, 2020). "At the same time, UCA1 expression was significantly upregulated in lung cancer patients with gefitinib resistance." (PMID 31777598, 2019). "For example, UCA1 can induce acquired resistance to EGFR-tyrosine kinase inhibitors (TKIs) in EGFR-mutant nonsmall cell lung cancer by activating the AKT/mTOR pathway." (PMID 30377411, 2018). "The lncRNA UCA1 levels were higher in lung cancer tissues from patients with acquired resistance to EGFR-TKIs compared to EGFR-TKI sensitive patients or patients with primary resistance to EGFR-TKIs." (PMID 28969100, 2017). "The UCA1 originally was identified in human bladder transitional cell carcinoma and highly expressed in lung cancer." (PMID 26949706, 2016). "Specially, UCA1 was predicted as the third candidate and confirmed by the recent observation that the overexpression of plasma UCA1 promoted the malignant progression of lung cancer." (PMID 27322210, 2016). "Several known lung cancer-associated lncRNAs, such as HOTAIR, GAS5, PVT1, and UCA1 were found in this top list which further supported the power of this analysis." (PMID 26862852, 2016). "To validate the analysis of lncRNAs profiles, we assessed the mRNA expression of UCA1 by RT-PCR in lung cancer cell lines and patients with EGFR-mutant NSCLC." (PMID 26160838, 2015).
lung cancer (continued). "One of important findings of this study was that over-expression of UCA1 in lung cancer cells and patients with acquired resistance to EGFR-TKIs." (PMID 26160838, 2015). "In our study, UCA1 expression was significantly increased in lung cancer cells and patients with acquired resistance to EGFR-TKIs." (PMID 26160838, 2015). "Over-expression of UCA1 was observed in lung cancer cells with acquired resistance (PC9/R and H1975) [P < 0.01]." (PMID 26160838, 2015). "Furthermore, curcumin inhibited the Wnt and mTOR signaling pathways through the downregulation of UCA1, suggesting that curcumin exerts its anticancer effects in lung cancer by targeting the UCA1–Wnt/mTOR axis (Wang W.-H." (PMID 41322307, 2025). "Similarly, the oncogenic functions of UCA1 have also been noted in other cancers, e.g. lung cancer, cervical cancer, ovarian cancer and a variety of other cancers." (PMID 38277283, 2024). "In addition, UCA1 interacts with miR-193a, leading to lung cancer via cell proliferation, apoptosis suppression, and metastasis in an ERBB4 and HMGB1-dependent way." (PMID 37245177, 2023). "We found the top 30 lncRNAs associated with lung cancers and inferred that lncRNAs TUG1, PTENP1, and UCA1 may be biomarkers of lung neoplasms, non-small–cell lung cancer, and LUAD, respectively." (PMID 35938010, 2022). "Furthermore, the application of antagomirs of miR‐138 or miR‐193 in lung cancer cells led to the enhancement of UCA1 RNA levels." (PMID 32767514, 2020). "Finally, the expression of miR‐138/193 and UCA1 was examined in lung cancer and adjacent normal tissues." (PMID 32767514, 2020). "In addition, lncRNAs such as DANCR, LINC00336, MNX1-AS1, LINC00673, SNHG4, LEF1-AS1, UCA1 (urothelial carcinoma-associated 1), SNHG1, and PTAR act as ceRNAs for miRNAs and exhibit oncogenic functions in lung cancer cells." (PMID 33412752, 2020). "PCR showed that UCA1 was highly expressed in lung cancer tissues compared with normal tissues." (PMID 32767514, 2020). "Li and colleagues showed that a high expression of UCA1 could develops cisplatin resistance in lung cancer cells via UCA1/miR-495/NRF2 crosstalk." (PMID 33287295, 2020). "In these patients, UCA1 overexpression was associated with a shorter progression-free survival in lung cancer patients without T790M genetic mutation status." (PMID 28904641, 2017). "Of note, UCA1 has been shown to be up-regulated in lung cancer and induce chemoresistance." (PMID 26160838, 2015). "Consequently, the modulation of the UCA1–miR-26a-5p/miR-144-3p axis may play a crucial role in inhibiting the proliferation of gastric and lung cancer cells." (PMID 37190145, 2023). "Similarly, UCA1 inhibits apoptosis in lung cancer by causing a G2/M cell cycle stop through a negative-influencing interaction with miR-143." (PMID 37245177, 2023). "LncRNA UCA1 could bind to heterogeneous nuclear ribonucleoprotein 1 by competing with p27 gene, thus inhibiting the expression of p27 and promoting the proliferation of lung cancer cells." (PMID 33976738, 2021). "However, the mechanism of UCA1 function, especially for its posttranscriptional regulation in lung cancer, remains unclear." (PMID 32767514, 2020). "Studies have found that UCA1 is highly expressed in NSCLC tissues, and silencing UCA1 will reduce the proliferation ability of lung cancer cells including NSCLC." (PMID 35963868, 2022). "The highest expression levels for ZEB1‐AS and UCA1 were identified on A549, NCI‐H2347, NCI‐H1975 and HCC827 lung cancer cells." (PMID 33433063, 2021). "Although several lncRNAs such as JPX, UCA1, and JHDM1D-AS1 have been reported to coordinate lung cancer progression, most aberrantly expressed lncRNAs in lung cancer remain uncharacterized." (PMID 33618674, 2021). "Regarding lung cancer, the up regulation of a potent oncogene, ERBB4, generated by UCA1 was achieved by binding miR-193-3p." (PMID 33422052, 2021).
lung cancer (continued). "We filtrated expression of lncRNAs in lung cancer cells after sevoflurane treatment, namely PCAT6, UCA1, SNHG1, CCAT2, and found that the level of PCAT6 was significantly suppressed after sevoflurane administration." (PMID 33987473, 2020). "In recent years, a growing number of studies have shown that UCA1 up-regulated in several cancers, including HCC, GC and lung cancer." (PMID 30918102, 2019). "The expression of UCA1 in a normal human lung bronchial epithelial cell line (16-HBE) and human lung cancer cell lines (A549, H1299, H522, 95D, and H358) was determined using qRT-PCR." (PMID 35540445, 2018). "To date, multiple lncRNAs, including MALAT1, UCA1, SPRY4-IT1, CCAT2, AFAP1-AS1 and BANCR, have been confirmed to be promising prognostic indicators in lung cancer patients." (PMID 29137343, 2017). "We have identified some lncRNAs including lncRNA UCA1, H19, BC200 and BC087858 were up-regulated in gefitinib-resistant human lung cancer cells by lncRNA microarray analysis." (PMID 27409677, 2016). "For instance, in related studies super-enhancer-regulated lncRNA UCA1 has been found to serve as an endogenous competitive RNA binding miR-193a-3p to regulate ERBB4, thereby promoting proliferation and colony formation of lung cancer cells." (PMID 35663324, 2022). "We have demonstrated using in vitro cisplatin or TKI‐erlotinib treatment, routinely used in human lung cancer therapy schemes, a significant induced overexpressed LncRNA SOX2‐OT level, in contrast with other LncRNAs, such as GLI1‐AS, GAS5, ZEB1‐AS, and UCA1." (PMID 33433063, 2021). "In human lung cancer tissues, our results showed a significant negative correlation between miR‐138 or miR‐193, and UCA1 in lung cancer tissues." (PMID 32767514, 2020). "In human lung cancer tissues, our study showed a significant negative correlation between miR‐138 or miR‐193 and UCA1 in lung cancer tissues." (PMID 32767514, 2020). "Thus, we subsequently conducted a meta-analysis to assess the relationships between LINC01133, UCA1 and PVT-1 expression and OS in lung cancer patients." (PMID 29137343, 2017). "In the present study, we sought to determine whether the lncRNA UCA1 can induce acquired resistance to EGFR-TKIs via cell apoptosis and activation of the PI3K/AKT/mTOR pathway in EGFR-mutant lung cancer." (PMID 26160838, 2015). "Moreover, there was a significant negative correlation between miR‐138 and miR‐193 and UCA1 in lung cancer tissues." (PMID 32767514, 2020). "Similarly, MALAT1, UCA1, ANRIL, and NEAT1 were shown to predict lung cancers." (PMID 31141943, 2019). "The latest reports indicate some lncRNAs, such as PCGEMI, UCA1, lincRNA-p21 and CRNDE play a positive role in cancer cell glucose metabolism to contribute to the Warburg effect, however, it remains largely unknown whether and how lncRNA regulates cellular energy metabolism in lung cancer." (PMID 28946875, 2017).